DLG1 (discs large MAGUK scaffold protein 1)
Diseases named in the same sentence as DLG1 in open-access papers (continued):
Sharing a sentence is not in itself a finding about the gene and the disease.
cyst (3 papers, 2018 to 2019). A sac-like closed membranous structure that may be empty or contain fluid or amorphous material. "Together, these results reaffirmed that loss of Dlg1 and NrxIV from the SCCs during the mitotic–meiotic transition blocks cyst differentiation and leads to eventual loss of germ cells beyond the early spermatogonial stages." (PMID 30635267, 2019). "Together, these observations suggested that loss of Dlg1 in the SCCs disrupted NBs during cyst rotation through the TE before sperm release." (PMID 30635267, 2019). "Time-lapse imaging further indicated that the spermatids are likely to be released during the cyst rotation in the terminal epithelium (TE) region at the base of the testis in the dlg1 RNAi background." (PMID 30635267, 2019). "Dlg1 is involved in the establishment of polarity in fruit flies and required for adherens junction formation in C. elegans, and while its role in mammalian epithelial polarity is less clear, if loss of Dlg1 globally affected the polarity of the cyst this might indirectly affect spindle orientation." (PMID 31289196, 2019). "It reduced the eyes-absent (Eya)-positive SCCs and induced germ cell death in the 16-cell spermatocyte cysts, indicating a role of Dlg1 in somatic differentiation as well as cyst survival." (PMID 30635267, 2019). "Although tj-Gal4 mediated knockdown of Dlg1 in SCCs during the spermatogonial stages disrupted the cyst permeability barrier and arrested differentiation, it did not affect the transit amplifying divisions of the spermatogonia." (PMID 30635267, 2019). "Hence, we conclude that the loss of Dlg1 in SCCs leads to loss of SJs between the HCC and TCC, and that the integrity of this junction is critical to prevent cyst disruption and premature sperm release within the testis." (PMID 30635267, 2019). "We found that somatic loss of Arm/β-catenin, and that of the septate junction proteins NrxIV and Dlg1, could independently disrupt the integrity of somatic cyst enclosure." (PMID 30045884, 2018). "The spermatid heads were labeled with ProtamineA-GFP and cyst cell membrane was labeled with PpY>mCD8-RFP in both the control (ProtA-GFP/UAS-Dicer; PpY-Gal4>UAS-mCD8-RFP/+) and dlg1 RNAi (ProtA-GFP/UAS-dsDlg1; PpY-Gal4>UAS-mCD8-RFP/+) backgrounds." (PMID 30635267, 2019).
depression (3 papers, 2021 to 2023). "Collectively, our studies elucidate that Dlg1 microglia-specific knockout not only mitigates inflammation-initiated depression, but also stress-induced depression as well as associated microglial activation." (PMID 36909184, 2023). "In our previous study, we demonstrated that microglial Dlg1 is a regulator of NF-κB signaling, and Dlg1 deletion inhibits microglial activation and inflammatory cytokine production, thereby alleviating LPS-induced depression behavior." (PMID 36909184, 2023). "Given that Dlg1 knockdown significantly reduced the inflammatory response in microglia, we next sought to explore the role of Dlg1 in depression." (PMID 34490521, 2021). "Our findings demonstrate that Dlg1 plays a vital role in microglial activation and provides a potential therapeutic target for the treatment of depression." (PMID 34490521, 2021). "In summary, our results demonstrated that Dlg1 plays a critical role in microglial activation and thus provides a potential therapeutic target for the clinical treatment of depression." (PMID 34490521, 2021). "In this study, we found that knockout of Dlg1 in microglia alleviated neuroinflammation-induced depression-like behaviors in mice, providing a novel way to interfere with microglial activation and an alternative treatment strategy for depression." (PMID 34490521, 2021). "Microglial Dlg1 deletion ameliorates the symptoms of depression in mice, and the hippocampus is relatively vulnerable to acute inflammatory attack during depression." (PMID 34490521, 2021). "Consistent with the results in the TST, microglial Dlg1 knockdown significantly decreased the immobility time, suggesting an improvement in depression-like behavior." (PMID 34490521, 2021). "Our results demonstrated that Dlg1 knockout reduced microglial activation and inflammatory cytokine levels in the hippocampus, suggesting that Dlg1 functions as an important regulator of inflammation-induced depression." (PMID 34490521, 2021). "In vivo, conditional knockout of microglial Dlg1 inhibited microglial activation, decreased inflammatory cytokine levels, and alleviated depression-like behaviors in mice, providing a potential therapeutic strategy to treat or slow down the progression of depression." (PMID 34490521, 2021). "To evaluate the role of microglial Dlg1 on depression, we established chronic restraint stress (CRS) model, which has higher etiological similarities to depression." (PMID 36909184, 2023). "In this study, we demonstrated that Dlg1 ablation in microglia remarkedly reversed microglial activation and depression-like behavior in mice induced by exposure to CRS, indicating a potential target to suppress microglial activation, limit neuroinflammation, and thereby ameliorate depression." (PMID 36909184, 2023).
Intellectual disability (3 papers, 2019 to 2023). "For example, human orthologs to fly genes CASK (CASK), Mnb (DYRK1A), Dlg-1 (DLG1), Cdc42 (CDC42), Fmr1 (FMR1, FXR1/2), trio (TRIO), Nedd4 (NEDD4L/NEDD4) and CamKII (CAMK2A/B/D) have been linked to intellectual disability." (PMID 37759179, 2023). "This deletion is different from the canonical region, as it does not include the PAK2 and DLG1 genes, considered as candidates for causing intellectual disability." (PMID 31338352, 2019).
neuroblastoma (3 papers, 2020 to 2022). Neuroblastoma (NB) is the most common solid, extracranial childhood tumor. "We evaluated the DLG gene family and the LIN7 gene family for their expression in differently INSS staged neuroblastoma from publically available data and primary tumors, we included two distinct DLG1 and DLG2 N-terminal transcript isoforms encoding L27 domains for their expression." (PMID 33726762, 2021). "Whilst DLG1 showed a decrease in both isoforms with increased INSS stage, only the full length L27 containing DLG2 transcripts DLG2-isoform 7/8 showed a decrease in expression in high stage neuroblastoma." (PMID 33726762, 2021). "SH-SY5Y neuroblastoma cells in which TDP-43 expression had been greatly reduced by treatment with an anti-TDP-43 RNAi showed a concomitant, clear downregulation of the Dlg homolog protein SAP-97/DLG1." (PMID 32216790, 2020).
colon cancer (2 papers, 2015 to 2024). "High expression of DLG1 was found to be associated with tumor invasiveness in colon cancer, while some scholars have found that DLG1 played an inhibitory role in liver cancer and inhibited its metastasis.So far, the role of DLG1 in pancreatic cancer and its related mechanism have not been reported." (PMID 38789418, 2024). "Of particular interest, three additional PDZ proteins—DLG1, CASK, and LIN7A—were detected in SW480 colon cancer cells, suggesting additional, yet to be characterized, ADRA1D complexes exist and are cell-type dependent." (PMID 26617989, 2015).
Crohn disease (2 papers, 2014 to 2016). A gastrointestinal disorder characterized by chronic inflammation involving all layers of the intestinal wall, noncaseating granulomas affecting the intestinal wall and regional lymph nodes, and transmural fibrosis. "Genetic variants in DLG5 (a human homolog of C. elegans dlg-1 and Drosophila dlg) are associated with IBD, and intestinal permeability has been correlated with peripheral immune activation and clinical relapse in patients with Crohn’s disease." (PMID 26769134, 2016).
dementia (2 papers, 2014 to 2021). Loss of intellectual abilities interfering with an individual's social and occupational functions. "In this stratum, enrichment analysis of RRA cortex candidates showed an over-representation of genes involved in cardiac development and function (DLG1, JPH2 or MEF2C among others), supporting a cardiovascular etiology of dementia in this stratum." (PMID 33846280, 2021).
hepatocellular carcinoma (2 papers, 2020 to 2021). A malignant tumor that arises from hepatocytes. "Likewise, DLG1 downregulation was observed in the later stages of lung, laryngeal, breast, and hepatocellular cancers." (PMID 34503271, 2021).
liver cancer (2 papers, 2019 to 2024). An epithelial or non-epithelial malignant neoplasm that arises from the liver. "The hepatitis C virus, which is linked to the development of liver cancer, causes a mislocalisation of Dlg1 away from the cell cortex, which leads to multilumen formation in MDCKII cysts; our results indicate this is likely to involve misorientation of the mitotic spindle." (PMID 31289196, 2019).
lung carcinoma (2 papers, 2020 to 2025). "Five of the eight NSCLC/lung cancers harboring a RASGRF fusion were adenocarcinomas (corresponding to the NSCLCs containing PACSIN2-RASGRF1, DLG1-RASGRF1, RP2-RASGRF1, NPTN-RASGRF1, and OCLN–RASGRF2)." (PMID 40615519, 2025). "Besides no record about SCN8A, THPA confirmed a similar tendency for an increased expression of HDAC1, DLG1, EPHB2 and CALB1, while GDNF was not apparently changed in either normal or lung cancer tissues; no data were available for SCN8A." (PMID 32102656, 2020).
ventricular septal defect (2 papers, 2011 to 2015). The presence of a defect (opening) in the septum that separates the two ventricles of the heart. "All Dlg1-/- mice examined exhibited ventricular septal defect (VSD)." (PMID 25860837, 2015).
adenovirus infections (1 paper, 2017). "It is possible that the interaction with Tax not only interferes with DLG1 regulatory functions, but also induces some activities that contribute to Tax functions involved in the viral cycle and pathogenesis, as reported for other viral oncoproteins in HPV and adenovirus infections." (PMID 29168728, 2017).
cardiac hypertrophy (1 paper, 2025). "AC5 was also proximal to the PKA scaffolding protein AKAP12, along with the discs large MAGUK-scaffold protein 1 (DLG1) which may help to assemble stress-responsive nanodomains for cardiac hypertrophy." (PMID 40749829, 2025).
cardiomyopathies (1 paper, 2017). "Furthermore, variants in AKAP9 and DLG1 genes could act as genetic modifiers of arrhythmic risk and phenotype severity in cardiomyopathies." (PMID 28750076, 2017).
cervical disease (1 paper, 2020). "DLG1 expression associates with the progress of cervical disease." (PMID 33679866, 2020).
cervical intraepithelial neoplasia (1 paper, 2008). "A similar process of translocation of the Dlg1 protein occurs in cervical intraepithelial neoplasia." (PMID 19098995, 2008).
cervical squamous cell carcinoma (1 paper, 2023). A squamous cell carcinoma arising from the cervical epithelium. "We focused on keratinocytes given that we had previously shown Cx43 interaction with Dlg1 in precancerous HPV-infected cervical keratinocytes and cervical squamous cell cancer cell lines." (PMID 37288673, 2023).
cervical squamous intraepithelial lesions (1 paper, 2020). "Interestingly, in cervical squamous intraepithelial lesions, alterations in DLG1 expression were observed in association to tumour progression." (PMID 32264889, 2020).
cocaine addiction (1 paper, 2022). "In addition, decades of research on cocaine addiction have revealed that several genes such as deltaFosB, Dlg1, JunB, and AMPA receptor subunit GluR221,22, are implicated in cocaine addiction." (PMID 35469040, 2022).
colonic disease (1 paper, 2014). "After intravenous injection with six cycles of infliximab, the affected daughter in Family A has almost achieved mucosal healing of her colonic disease and was likely to have a better prognosis than those DLG1 mutation carriers who did not accept infliximab treatments in our study." (PMID 24937328, 2014).
colorectal cancer (1 paper, 2022). A primary or metastatic malignant neoplasm that affects the colon or rectum. "Studies using patient-derived colorectal cancer organoids to compare BRAF fusions with various fusion partners (TRIM24, AGAP3, and DLG1) have shown that the 5′ partner plays a role in signaling and localization that affects signaling pathways and gene expression." (PMID 35326655, 2022).
Cyanosis (1 paper, 2015). Bluish discoloration of the skin and mucosa due to poor circulation or inadequate oxygenation of arterial or capillary blood. "Because Dlg1-/- infant mice exhibit respiratory failure and cyanosis, we suspected a defect in the cardiovascular system and examined the gross anatomy of the heart outflow tract in Dlg1-/- mice at E18.5." (PMID 25860837, 2015).
gastric cancer (1 paper, 2021). A primary or metastatic malignant neoplasm involving the stomach. "The expression of circRNA discs large homolog 1 (DLG1) was determined in a larger cohort of primary and distant metastatic gastric cancer tissues." (PMID 34911533, 2021). "We found that the circRNA circDLG1 (hsa_circ_0008583), which is derived from the DLG1 gene, was significantly upregulated in distant metastatic tissues and primary gastric cancer tissues resistant to anti-PD-1 therapy." (PMID 34911533, 2021). "However, only hsa_circ_0008583 (derived from exons 13, 14, 15 and 16 of DLG1, thus designated circDLG1) was confirmed to be upregulated in distant metastatic lesions and primary gastric cancer tissues resistant to anti-PD-1 therapy in a larger cohort of patients." (PMID 34911533, 2021).
HIV-1 infection (1 paper, 2012). The type species of lentivirus and the etiologic agent of acquired immunodeficiency syndrome (AIDS). "Our results show that HIV-1 infection of Dlg1- Jurkat T cells results in progeny viruses with enhanced infectivity and that in these cells the early steps of the HIV-1 life cycle are not affected." (PMID 22272285, 2012). "In this study the possible implication of Dlg1 in HIV-1 infection of a natural target of the virus was investigated in T cells depleted of Dlg1." (PMID 22272285, 2012). "Kinetics of HIV-1 infection in Dlg1-depleted Jurkat T cells show that Dlg1 modulates the replication of HIV-1." (PMID 22272285, 2012). "Therefore, these cells can be used to further study the possible role of Dlg1 in VS formation and virus transmission during HIV-1 infection." (PMID 22272285, 2012).
human papillomavirus infection (1 paper, 2021). "Previous work has demonstrated that the Scribble complex members DLG1 and/or SCRIB play key roles facilitating ARHGEF26 activity and RHOG activation during human papillomavirus infection, as well as in regulating epithelial junction formation, contractability, and lumen formation in 3D cysts." (PMID 34242364, 2021).
hydronephrosis (1 paper, 2024). Collection of urine in the renal pelvis that results in dilatation of the renal pelvis and calyces. "These mice display a congenital hydronephrosis phenotype similar to that observed in the global Dlg1−/− mutant mice, as well as tubular dilations that appeared to be pre-cystic." (PMID 38849673, 2024). "The Pax3Cre transgene is also active in urogenital mesenchyme, and it was concluded that the lack of DLG1 in these cells results in the observed structural and functional defects in the ureter that cause hydronephrosis." (PMID 38849673, 2024).
influenza infection (1 paper, 2013). "Increased expression of DLG1 protein was reported in influenza infection and interaction of the viral NS1 segment with DLG1 has been implicated in tight junction disruption." (PMID 24116168, 2013).
long QT syndrome (1 paper, 2023). "Results strongly suggest that DLG1 loss-of-function variants are associated with long QT syndrome, whereas gain-of-function ones with BrS." (PMID 36833354, 2023).
mental disorder (1 paper, 2025). A disease that has its basis in the disruption of mental process. "Dysfunction of the Dlg family has been implicated in several mental disorders: Dlg4 (also known as PSD95 or SAP90), Dlg1 (also known as SAP97), and Dlg2 (also known as PSD93 or Chapsin110)." (PMID 40360818, 2025).
Nicotine addiction (1 paper, 2025). "Among these, the TGF-beta signaling pathway, T cell receptor signaling pathway, and Nicotine addiction pathway were highly enriched (p < 0.01) enriched involving relevant genes (PITX2, ID4, BMP4, DLG1, IKBKB, ICOS, GRIA3, and SLC17A6)." (PMID 40496916, 2025).
ocular cancer (1 paper, 2008). A benign or malignant neoplasm affecting the structures of the eye. "The aim of our study was to investigate the gene expressions and protein distribution and levels for mouse Dlg1, Scrib, and Lgl1 during mouse tumorigenesis in this transgenic model of ocular cancer and to establish their potential involvement in the malignancy process." (PMID 19098995, 2008).
ocular tumor (1 paper, 2008). "Consistent with our results, the altered localization of Dlg1, Lgl1, and Scrib appeared to be associated with dysplasic stages whereas their downregulation could be considered as a late stage marker in the progression of ocular tumor development." (PMID 19098995, 2008). "In summary, both RT–PCR and western blotting revealed a downregulation of Dlg1, Scrib, and Lgl1 in whole eyes from Trp1/Tag transgenic mice with an inverse correlation observed reproducibly between protein levels and the tumor invasion stage in our ocular tumor model." (PMID 19098995, 2008). "However, whereas Dlg1 mRNA was not reduced at three months of age in the ocular tumor total RNA samples, we found that the protein levels were still low at this stage compared to the control mice." (PMID 19098995, 2008).
orofacial cleft (1 paper, 2019). A disorder of facial skeleton that is characterized by cleft lip and/or cleft palate that result in feeding, speech and hearing problems caused by failures during development. "Individuals with a 3q29 interstitial microdeletion syndrome, including the DLG1 gene, have orofacial cleft in 4% to 9% of cases." (PMID 31652620, 2019).
oropharyngeal cancer (1 paper, 2021). Carcinoma, predominantly squamous cell, arising from the epithelial cells of the oropharynx. "This is the first study to analyze the cause-and-effect relationship of DLG1 and SCRIB protein expression levels in a panel of HPV-negative and HPV-positive histologic oropharyngeal cancer samples." (PMID 34503271, 2021).
oropharyngeal squamous cell carcinomas (1 paper, 2021). "We investigated how modifications in the cellular localization and protein expression of DLG1 and SCRIB in HPV16-positive and HPV-negative histologic oropharyngeal squamous cell carcinomas (OPSCC) might reflect disease progression." (PMID 34503271, 2021).
pancreatic cancer (1 paper, 2024). "The DLG1 expression level was less abundant in pancreatic cancer tissues compared with para-cancerous tissues." (PMID 38789418, 2024).
pituitary tumor (1 paper, 2022). A benign or malignant neoplasm affecting the pituitary gland. "To verify the effect of mutant SF3B1 on DLG1 in vitro, we infected primary cultured pituitary tumor cells with adenovirus carrying the SF3B1-R625H mutation, and the results showed that the cryptic DLG1 transcript was observed in the Ad-SF3B1-R625H group." (PMID 35039052, 2022).
respiratory failure (1 paper, 2015). The significant impairment of gas exchange within the lungs resulting in hypoxia, hypercarbia, or both, to the extent that organ tissue perfusion is severely compromised. "Null mutant mice for the Dlg1 gene (Dlg1-/- mice) exhibit respiratory failure and cyanosis, and die soon after birth." (PMID 25860837, 2015).
Retinal dysplasia (1 paper, 2008). Abnormal growth and differentiation, structure and appearance of the retina present from birth. "In the peripheral retina, retinal dysplasia was also associated with reduced Dlg1 labeling in the OPL as described in the central retina." (PMID 19098995, 2008).
retinitis pigmentosa 55 (1 paper, 2024). "Both DLGAP1 and DLG1 are associated with retinitis pigmentosa 55, a disorder characterized by photoreceptor loss and reactive pigment changes in the RPE starting in the mid-peripheral fundus." (PMID 39337590, 2024).